RHOA (ras homolog family member A)
Diseases named in the same sentence as RHOA in open-access papers (continued):
Sharing a sentence is not in itself a finding about the gene and the disease.
congenital heart disease (1 paper, 2025). A heart disease that is present at birth. "Furthermore, a nonsense variant in the RHOA gene has been reported in the scientific literature as potentially linked to congenital heart disease." (PMID 41153384, 2025).
coronary atherosclerosis (1 paper, 2016). Atherosclerosis of the coronary vasculature. "Our study presents an interesting opportunity for the potential application of RhoA/ROCK inhibitors or transplantation approach using MMP3-overexpressed MSCs in patients with coronary atherosclerosis or post coronary angioplasty." (PMID 27126736, 2016).
cowpox (1 paper, 2020). A mild, eruptive skin disease of milk cows caused by cowpox virus, with lesions occurring principally on the udder and teats. "RHOA, encoding a small GTPase protein in the Rho family of GTPases, is connected to SARS-CoV-2, cowpox, and HSV-2 as well." (PMID 33156843, 2020).
demyelinating disease (1 paper, 2022). A broad group of disorders that affect the myelin sheaths that cover the neurons. "In any event, the CB1 receptor-evoked control of RhoA signaling could be potentially targeted to promote functional recovery, which would open new avenues to the therapeutic manipulation of currently intractable demyelinating diseases." (PMID 35798697, 2022).
diabetic retinopathy (1 paper, 2021). "TGR5, a bile acid receptor, has been previously reported to activate PKA signaling by increasing intracellular cAMP levels, and activation of TGR5 receptors can relive diabetic retinopathy by inhibiting the RhoA/ROCK pathway." (PMID 34365464, 2021).
ductal breast carcinomas (1 paper, 2017). "In contrast, an absent RhoA staining was found in most cases and tissue specimens of normal epithelium, DCIS and ductal breast carcinomas, except for three out of nine cases showing weak cytoplasmic RhoA protein expression in DCIS and/or ductal breast carcinomas (case 9)." (PMID 29152087, 2017).
edema (1 paper, 2014). An abnormal accumulation of fluid beneath the skin, or in one or more cavities of the body. "This study showed that high tidal volume ventilation increased total protein, IL-1β, IL-6, RANTES, neutrophil counts, and MPO activity in the BALF and induced lung edema, GEF-H1 and active RhoA expression, Rho-kinase activation, and ultrastructural evidence of endothelial destruction." (PMID 25019086, 2014).
fungal infections (1 paper, 2024). "Interestingly, our bioinformatics analysis showed that host interactors were enriched in DARPP-32 events at high levels, and other interactors, including RHOA and PPP2CA, prompting us to explore the possibility of non-neurological functions of DARPP-32, especially its role in fungal infections." (PMID 38413612, 2024).
gallbladder cancer (1 paper, 2025). "PA was investigated for its potential to inhibit migration/invasion and reduce RhoA expression in gallbladder cancer cells." (PMID 40699710, 2025).
hantavirus infections (1 paper, 2016). "The central importance of RhoA activation in MEC permeability further suggests therapeutically targeting RhoA, TSCs, and Rac1 as potential means of resolving capillary leakage during hantavirus infections." (PMID 27795403, 2016). "Additional MEC functions dysregulated by hantavirus infection may also exacerbate N-protein-directed RhoA activation." (PMID 27795403, 2016).
Hearing impairment (1 paper, 2023). A decreased magnitude of the sensory perception of sound. "We propose that a hemizygous missense variant in DIAPH2 (p.I290V) on the X-chromosome may underlie the progressive hearing impairment in a family of Italian origin, possibly impairing RhoA-dependent activation of DIAPH2." (PMID 36689403, 2023).
Hydrocephalus (1 paper, 2017). Hydrocephalus is an active distension of the ventricular system of the brain resulting from inadequate passage of CSF from its point of production within the cerebral ventricles to its point of absorption into the systemic circulation. "Increased RhoA activity after deletion of myosin IXa (Myo9a), a motor molecule with a Rho GTPase‐activating (GAP) domain, leads to hydrocephalus formation in mice." (PMID 28500065, 2017).
hypogonadism (1 paper, 2020). A disorder characterized by decreased function of the gonads. "Estradiol could revert hypogonadism-induced downregulation of RhoA/ROCK pathway and restore epididymal contractility." (PMID 32728148, 2020).
hypoxia (1 paper, 2022). A decrease in the amount of oxygen in the body. "Although the significance of the RhoA/ROCK1 signaling pathway has been well recognized in preretinal neovascularization diseases, its relevant regulation in hypoxia-induced retinopathy has not been clearly explored." (PMID 35006271, 2022).
inflammatory skin disease (1 paper, 2025). Inflammatory skin disorders covers a broad category that includes many conditions ranging in severity, from mild itching to grave medical health complications These disorders are common in people of all ages and races. "Targeting the KDR/GEF-H1/RhoA pathway may reduce keratinocyte inflammatory responses, providing benefits in inflammatory skin disease." (PMID 40746859, 2025).
invasive breast ductal carcinoma (1 paper, 2018). "The disruption of the activity of RhoA or Rac1/Cdc42 is associated with malignancy, and in invasive breast ductal carcinoma, the overexpression of either RhoA or Rac1 have been associated with worse prognosis." (PMID 29535813, 2018).
invasive carcinoma (1 paper, 2017). A carcinoma that is not confined to the epithelium, and has spread to the surrounding stroma. "To unravel the contribution of RhoA and RhoC during the development of non-transformed breast epithelial cells to invasive carcinoma, we established stable MCF-10A cell lines, in which expression of RhoA or RhoC can be induced by doxycycline." (PMID 29152087, 2017).
ischemic disease (1 paper, 2022). Lack of blood supply to an area of the body, resulting in impairment of tissue oxygenation. "Our data suggest that pathways involved in RhoA signaling could serve as druggable targets to facilitate mitophagy to prevent ischemic disease." (PMID 35760846, 2022).
Kaposi's sarcoma (1 paper, 2015). A malignant neoplasm characterized by a vascular proliferation which usually contains blunt endothelial cells. "Our study shows that the Kaposin B (KapB) protein of Kaposi's sarcoma (KS)-associated herpesvirus, known to block the degradation of a class of labile host mRNAs, does so by constitutively activating a signaling axis involving MK2, hsp27, p115RhoGEF and RhoA, thereby dispersing PBs." (PMID 25569678, 2015).
kidney cancer (1 paper, 2021). Primary or metastatic malignant neoplasm involving the kidney. "RhoA-GTP, an active form of RhoA, was increased by about 30% in kidney cancer cells with knockdown of FLCN, which co-localizes and interacts at the midbody during cytokinesis with p00717." (PMID 34031471, 2021).
Kidney Cyst (1 paper, 2020). Abnormal fluid filled sac within the kidney, either acquired or congenital. "RNA expression profiling of ADPKD and Pkd1–/– kidney cysts compared with healthy kidney tissue supports the targeting of the RhoA-YAP-cMyc axis, but wider profiling could be useful to identify other pathways to target at specific timepoints in cystogenesis or for particular genotypes." (PMID 33392209, 2020).
kidney failure (1 paper, 2016). An acute or chronic condition that is characterized by the inability of the kidneys to adequately filter the blood. "Cdc42 deletion results in massive neonatal proteinuria, kidney failure, and associated death within 2 weeks of birth, podocyte-specific RhoA and Rac1 deletion mutants are conspicuously healthy." (PMID 26986510, 2016).
language disorder (1 paper, 2022). A category of disorders characterized by an impairment in the development of an individual's language capabilities, which is in contrast to his/her non-verbal intellect. "RHOA activity, cell de-adhesion, cell division, and neural progenitor cells present new avenues to explore how changes in ARHGEF39 may contribute to neural development and to language disorder." (PMID 35959104, 2022).
latent infection (1 paper, 2025). "Recently, our group published a study describing US28-mediated activation of RhoA to enhance emergence out of latent infection and that pharmacologic inhibition of US28-mediated RhoA signaling blocks viral reactivation in vitro and in vivo." (PMID 39655954, 2025).
lentivirus infection (1 paper, 2011). Virus diseases caused by the Lentivirus genus. "Lentivirus infection with the constitutively active RhoA (L63) sequence dramatically promoted the cell migration towards the wound site and accelerated the wound healing process induced by activin B, whereas the dominant negative RhoA (N19) based infection delayed wound closure." (PMID 21949871, 2011). "To definitively determine the role of JNK in RhoA-mediated wound healing, we investigated the effect of JNK inhibition by SP600125 on RhoA activation (using RhoAL63 lentivirus infection)-promoted wound healing after activin B treatment." (PMID 21949871, 2011).
linitis plastica (1 paper, 2025). "Proximal GSRCC often exhibits diffuse infiltration (linitis plastica) and may harbor features like RHOA mutations and chromosomal instability, which can limit chemotherapeutic efficacy." (PMID 40723283, 2025).
lymphoblastic lymphoma (1 paper, 2009). A lymphoma composed of immature small to medium-sized precursor lymphoid cells (lymphoblasts). "Cantrell’s group has also shown that the elimination in thymocytes of RhoA function, a GTPase activated by Vav family proteins, leads to a lymphoblastic lymphoma very similar to the disseminated tumors found in Vav1–/– and Vav1–/–;Rasgrf2–/– mice." (PMID 20011522, 2009).
lymphoproliferative disorders (1 paper, 2016). "In this commentary, after briefly discussing recent work on the role of RhoA and the ROCKs in the development and activation of lymphocytes, we will highlight new findings that may link dysregulation of this pathway to a growing list of autoimmune and lymphoproliferative disorders." (PMID 27785353, 2016). "The multifaceted involvement of the RhoA-ROCK pathway in T and B cell biology has resulted in an increasing appreciation that dysregulation of this pathway may play potential pathophysiological roles in autoimmune and lymphoproliferative disorders." (PMID 27785353, 2016).
malignant meningioma (1 paper, 2016). "In our hands, targeting of DLC1-v1 with specific shRNA in KT21cells established from human malignant meningioma resulted in enhanced activity of RhoA/RhoB/RhoC GTPases as shown in active RHO pull down assay and increased cell migration in scratch assay." (PMID 27614886, 2016).
meningioma (1 paper, 2018). A generally slow growing tumor attached to the dura mater. "RHOA-ROCK-LIMK kinase activation was seen after AKAP12 knockdown indicating that AKAP12 may regulate RHOA-ROCK-LIMK pathway in grade II meningiomas." (PMID 29391485, 2018).
Menorrhagia (1 paper, 2023). Prolonged and excessive menses at regular intervals in excess of 80 mL or lasting longer than 7 days. "Other studies have reported that high expression of RhoA and Rock1 were positively associated with the severity of menorrhagia and menstrual volume in AM." (PMID 36969843, 2023).
mood disorder (1 paper, 2017). A cognitive disorder a disturbance in which the person's mood is hypothesized to be the main underlying feature. "Thus, activation of GPR55 links the RhoA-ROCK and PLC-PKC pathways to the development of mood disorders, evident by alteration of the expression of glutamate receptors." (PMID 28800762, 2017).
mouth neoplasm (1 paper, 2014). "The hsa-miR-31* has validated target, RhoA, which is reportedly implicated in mouth neoplasm." (PMID 25126847, 2014).
multiple symmetric lipomatosis (1 paper, 2020). A rare subcutaneous tissue disease characterized by growth of symmetric non-encapsulated masses of adipose tissue mostly around the face and neck with variable clinical repercussions (e.g. reduced neck mobility, compression of respiratory structures). "miR-483-5p, in coordination with miR-125-3p, is identified as a promoter of adipogenesis via the suppression of the RhoA/ROCK1/ERK1/2 pathway, and their studies may prove as a strategy to treat obesity or multiple symmetric lipomatosis (MSL)." (PMID 32992741, 2020).
muscular dystrophy (1 paper, 2020). Muscular dystrophy (MD) refers to a group of more than 30 genetic diseases characterized by progressive weakness and degeneration of the skeletal muscles that control movement. "Our findings implicate a novel role of RhoA in regulating the activation and function of macrophages that promote the histopathology and muscular dystrophy in dKO mice." (PMID 33361519, 2020). "Inhibition of RhoA could therefore represent a novel therapeutic approach to reduce musculoskeletal pathologies induced by chronic inflammation during the progression of disease in muscular dystrophy." (PMID 33361519, 2020).
myeloproliferative disease (1 paper, 2021). "One FLT3 mutant was found to activate Rho kinase through activation of RhoA small GTPase, resulting in myeloproliferative disease development." (PMID 34811450, 2021).
neuroma (1 paper, 2014). A tumor that grows from a nerve or is composed of nerve cells and nerve fibers. "Hence, the RhoA-ROK signaling may be involved in the nerve capping procedure and might develop new strategy in the management of painful neuromas." (PMID 24705579, 2014).
obstructive sleep apnea syndrome (1 paper, 2019). Cessation of air flow during sleep due to upper airway obstruction. "RhoA-Rock and ROS in obstructive sleep apnea syndrome induce chronic intermittent hypoxia, resulting in elevated BP." (PMID 31174369, 2019). "RhoA-Rock and ROS in obstructive sleep apnea syndrome induce chronic intermittent hypoxia, resulting in elevated blood pressure (BP)." (PMID 31174369, 2019).
osteopetrosis (1 paper, 2023). Osteopetrosis, also known as marble bone disease, is a descriptive term that refers to a group of rare, heritable disorders of the skeleton characterized by increased bone density on radiographs. "Conditional deletion of RhoA in the osteoclast lineage causes a severe osteopetrosis phenotype, which is attributable to a bone resorption suppression." (PMID 37020186, 2023). "We here show that conditional knock-out RhoA in the osteoclast lineage restrains RANKL induced osteoclast formation and activity through inhibition of NFATc1 resulting in a severe osteopetrosis mouse phenotype." (PMID 37020186, 2023). "Our findings have demonstrated that the absence of RhoA in osteoclast lineage impaired osteoclast formation and activity, leading to an osteopetrosis phenotype in mice." (PMID 37020186, 2023).
osteoradionecrosis (1 paper, 2020). Necrosis of bone following radiation injury. "In the light of these findings, the RhoA/ROCK signaling pathway might be a promising target for modifying the therapeutic effect of LIPUS on osteoradionecrosis." (PMID 32952571, 2020). "The mechanism may lie in the significant elevation of the expression of RhoA, ROCK, vinculin, and the ratio of p-FAK/FAK by regulating the RhoA/ROCK signaling pathway, thereby providing experimental evidence and modifying the target of LIPUS in osteoradionecrosis treatment practice." (PMID 32952571, 2020).
pancreatitis (1 paper, 2024). Inflammation of the pancreas. "The regulatory effects of S1P signaling on pancreatitis predominantly involve NF-κB, STAT3 phosphorylation, PERK/TXNIP/NLRP3, RhoA/ROCK, and AMPK/mTOR pathways as well as IFN-γ and TGF-β1." (PMID 39519028, 2024).
parathyroid tumors (1 paper, 2021). "Filamin A binds to and promotes activation of RhoA; therefore, filamin A and Gαq/11 downregulation occurring in parathyroid tumors may inhibit RhoA activation and the inhibitory effect of the Hippo signaling pathway on YAP1, contributing to reduction in YAP1 nuclear accumulation." (PMID 33670622, 2021).
periodontitis (1 paper, 2025). An acute or chronic inflammatory process that affects the tissues that surround and support the teeth. "The data demonstrate that the addition of mimic‐5107 or EPO‐EVs effectively targets EGFR and further enhances RhoA activity, thereby alleviating inflammatory bone loss in LPS‐induced mBMSCs and promoting alveolar bone development in periodontitis mouse models." (PMID 40289904, 2025). "In summary, our findings demonstrate that EPO‐EVs, highly enriched with miR‐5107‐5p, partially mitigate inflammatory bone loss in periodontitis through the EGFR/RhoA axis, suggesting a potential therapeutic target for periodontitis treatment." (PMID 40289904, 2025). "The abundant miR‐5107‐5p in EVs, following EPO stimulation, alleviates inflammatory bone loss in periodontitis mouse models through the EGFR/RhoA axis." (PMID 40289904, 2025).
peritonitis (1 paper, 2016). Inflammation of the peritoneum (tissue that lines the abdominal wall and covers most of the organs in the abdomen). "However we did note a significant decrease in gene expression of RHOA after peritonitis during high fat diet and therefore, we investigated RHOA activity after lipid loading." (PMID 26821597, 2016). "RhoA transcripts were down regulated during HFD peritonitis; therefore we investigated whether lipid loading inhibited monocyte cytoskeletal signaling." (PMID 26821597, 2016).
Peters anomaly (1 paper, 2024). Peters anomaly (PA) is a congenital corneal opacity disorder characterized by a central corneal leukoma that obstructs the pupil leading to visual loss as well as absence of the posterior corneal stroma and Descemet membrane. "Our results demonstrate that Abl kinases regulate FGF signaling to balance RhoA and Rac1 activity via the Ptpn12-p130Cas pathway, suggesting that targeting tension-mediated lens vesicle separation could be a therapeutic strategy for Peters anomaly." (PMID 39484567, 2024).
Pleural effusion (1 paper, 2018). The presence of an excessive amount of fluid in the pleural cavity. "The activated RhoA/ROCK pathway impairs endothelial barrier properties leading to increased paracellular permeability which could explain pleural effusion and edema formation." (PMID 29867576, 2018).
pneumococcal pneumonia (1 paper, 2022). A febrile disease caused by STREPTOCOCCUS PNEUMONIAE. "Deletion of UGRP1 or blocking UGRP1 interaction with PDPN protected mice against S. pneumoniae‐induced severe pneumococcal pneumonia, and activating RhoA with agonist in UGRP1‐deficient mice restored the reduced IL‐6 production." (PMID 35652821, 2022).
pneumonia (1 paper, 2016). An acute, acute and chronic, or chronic inflammation focally or diffusely affecting the lung parenchyma, caused by an infection in one or both of the lungs (by bacteria, viruses, fungi, or mycoplasma.). "In addition, our previous studies showed that p120 was involved in inflammatory responses in a RhoA dependent manner in acute pneumonia caused by LPS17 and mechanical scratch caused inflammatory response." (PMID 27586697, 2016).
polycystic kidney disease (1 paper, 2020). A usually autosomal dominant and less frequently autosomal recessive genetic disorder characterized by the presence of numerous cysts in the kidneys leading to end-stage renal failure. "The RhoA–YAP–c-Myc signaling axis has been demonstrated to promote the development of polycystic kidney disease." (PMID 32974348, 2020).
prostatic hyperplasia (1 paper, 2023). "Finally, we found that Y-27632 partially reversed prostatic hyperplasia in rats, suggesting the therapeutic potential of RhoA-ROCK in BPH." (PMID 37864185, 2023). "Finally, Y-27632 partially reversed prostatic hyperplasia in vivo, further suggesting the potential of RhoA-ROCK signaling in BPH treatment." (PMID 37864185, 2023).